VDR (vitamin D receptor)
Diseases named in the same sentence as VDR in open-access papers (continued):
Sharing a sentence is not in itself a finding about the gene and the disease.
cancer (continued). "The present study provides new insights into the potential roles of VDR in tumor progression and tumor immunity in human cancers, thus laying the foundation for further studies." (PMID 38639057, 2024). "VDR expression decreased in 8 types and increased in 12 types of cancer compared with normal tissues." (PMID 38639057, 2024). "One possible explanation is that chemotherapy leads to an increase in the more active nuclear pool of VDR in cancer cells (which disturbs the balance between cytoplasmic and nuclear VDR) and reduces cytoplasmic VDR in normal cells." (PMID 39411136, 2024). "Meanwhile, the relationship between VDR expression and tumor characteristics in some cancers is still unclear." (PMID 38639057, 2024). "This comprehensive pan-cancer analysis revealed the potential role of VDR in tumor progression and tumor immunity." (PMID 38639057, 2024). "We analyzed the correlation between VDR expression and various clinicopathological factors such as age, race, and cancer stage." (PMID 39268267, 2024). "VDR is an intracellular hormone receptor expressed in both normal epithelial and cancer colon cells at various levels." (PMID 39451780, 2024). "It has also been observed that VDR is either highly expressed or downregulated in many histological types of cancers." (PMID 38318147, 2024). "VDR is widely expressed in most cell types, and its expression is progressively reduced during tumor progression in many cancer types." (PMID 38666921, 2024). "VDR was also widely expressed in human cancers especially in tumors of digestive system and endocrine system." (PMID 38639057, 2024). "When we considered VDR-IRS as a dichotomous variable, only high cytoplasmic VDR-IRS in cancer cells was associated with a low rate of nodal metastases and vascular invasion, consistent with the observations above." (PMID 39411136, 2024). "Our analysis of the genetic makeup of the VDR gene across various cancers was conducted using the TCGA datasets." (PMID 39268267, 2024). "The current study conducted a pan-cancer analysis of VDR expression in CESC using TIMER, GEPIA, and UALCAN, and the results revealed that VDR expression was significantly upregulated in tumors across the three databases." (PMID 39268267, 2024). "In this study, we aimed to fill this knowledge gap by conducting a pan-cancer analysis of VDR in CESC using bioinformatics tools to better understand its prognostic and immunological implications." (PMID 39268267, 2024). "Calcitriol and its receptor VDR have antitumor effects as demonstrated by many experimental studies in different types of malignant tumors including bladder urothelial carcinoma." (PMID 38265102, 2024). "This association is believed to be explained by the antiproliferative and prodifferentiative effects of vitamin D receptor activation in various cancer cells." (PMID 38772934, 2024). "Due to its altered expression and function, the role of VDR in cancers has also been extensively studied." (PMID 37880985, 2024). "The VDR-IRS of cancer cells increased with the number of NAC cycles, and the expression of receptors in the cytoplasm of normal cells decreased." (PMID 39411136, 2024). "Supplementation improved the 25(OH)D levels, but the response varied by cancer type and VDR genotype." (PMID 39766100, 2024). "The study concluded that a more developed cancer translates into a predominant nuclear expression of the VDR when compared to the cytoplasmatic levels of this receptor." (PMID 38928369, 2024). "A pan-cancer analysis was conducted on VDR in CESC, with a focus on its expression and relationship with immune infiltration and genetic alterations." (PMID 39268267, 2024). "The role of the VDR has been established in the progression and prognosis of various types of cancer, including CESC." (PMID 39268267, 2024).
cancer (continued). "Due to immune cells such as macrophages have been shown to have opposing functions in regulating cancer progression, the definitive roles of VDR in tumor immunity remains to be further elucidated." (PMID 38639057, 2024). "This suggests the importance of the VDR for the anti-cancer activity of vitamin D hydroxy-derivatives since the level of tumor malignancy inversely correlates with VDR expression." (PMID 39456696, 2024). "The prognostic and immunological implications of the VDR in CESC through pan-cancer analysis are valuable but have limitations." (PMID 39268267, 2024). "We performed a comprehensive analysis of the relationship between VDR expression and a range of clinicopathological factors, including age, race, and cancer stage." (PMID 39268267, 2024). "Multiple studies have shown the relevance of the VDR in a great palette of cancers, ranging from prostate, skin, bladder, colon, ovary, breast, kidney, and lung to non-Hodgkin lymphoma, hepatocellular carcinoma, or thyroid carcinoma." (PMID 38928369, 2024). "Women with a positive menopausal status had higher VDR-IRS in cancer cells than in the remaining breast tissue (compared to those without menopause)." (PMID 39411136, 2024). "It was also reported that TNFα secreted by macrophages can inhibit VDR expression in cancer cells, whereas upregulation of VDR decreases the metastatic potential of 4T1 cells." (PMID 38355711, 2024). "Recent studies have found that VDR is abnormally expressed in various malignant tumours, such as prostate cancer, ovarian cancer, and breast cancer." (PMID 37046222, 2023). "Using both in vitro and in vivo systems, this work examined the influence of the VDR and vitamin D3 on the regulation and pathogenesis of OS through impact on OS growth, migration and potential cancer cell immunorecognition." (PMID 37228489, 2023). "In the pathological context of cancer, the VDR can directly or indirectly regulate the expression of >200 genes that influence cell proliferation, differentiation, and apoptosis, as well as immunomodulation and angiogenesis." (PMID 38203278, 2023). "It is, therefore, necessary to fill these gaps before considering VDR methylation signature as a biomarker of different grades and stages of cancer progression." (PMID 38203278, 2023). "Although numerous studies have implicated a suppressive role for vitamin D3 in invasive cancer development (e.g., breast, prostate) and improved cancer patient and animal survival, the functional role of vitamin D3 and the VDR in OS is unclear." (PMID 37228489, 2023). "Various AMPs, such as α-defensins, β-defensins, and LL-37, are involved in developing a variety of tumors and cancers, where the VDR regulates these peptides." (PMID 37317103, 2023). "Antagonism, for most of the selected targets (genes in purple), and agonism, for PGR, PPARA, and VDR (genes in red), were proposed as potential approaches for anti‐aging and anti‐cancer treatment." (PMID 37888486, 2023). "Phosphoinositide 3-kinase and mitogen-activated protein kinase downstream of ligand-bound VDR can be activated and modulate microRNA expression and cancer stem cell biology." (PMID 37383396, 2023). "Providing first causal evidence, further clinical and functional studies are necessary to assess if VDR is a suitable target for boosting immunotherapies against cancer." (PMID 37686465, 2023). "The JNK1/VDR connection generated calcitriol-mediated suppression of cancer cell growth through JNK1 activation." (PMID 38274206, 2023). "Species specificity was a confounding variable, in that vitamin D response elements were present in primates but not in mice, thus warranting caution for translational models regarding the utility of VDR as a target for cancer immunotherapy." (PMID 37686465, 2023). "The VDR/VitD-axis has been intensively investigated for more than a decade for the prevention and/or treatment of many cancers." (PMID 36902107, 2023).
cancer (continued). "Considering that cell migration and invasion into surrounding tissues are crucial steps for cancer metastasis, we detected the impact of VDR expression on CRC cell migration and invasion." (PMID 37046222, 2023). "In summary, calcitriol, the active form of VitD, exerts multiple effects on cancer cells by binding to the VDR." (PMID 37894739, 2023). "Increased VDR methylation levels have been observed in several cancer types and lead to reduced mRNA and protein expression levels, supporting the loss of an antiproliferative role of the VDR." (PMID 38203278, 2023). "This study indicated that VDR protected against CRC disease in humans by inhibiting Wnt/β-catenin signalling to control cancer cell invasion and apoptosis, providing new evidence to explore VDR biomarkers or agonists for CRC patient diagnosis and treatment." (PMID 37046222, 2023). "The main purpose of this literature review is to provide an up-to-date overview of the role of VDR methylation in different human disorders, including autoimmune and infectious diseases, cancer, and others." (PMID 38203278, 2023). "More recently, growing evidence has demonstrated that VDR protects against tumor progression of a number of common cancers such as prostate cancer, gastric cancer, and breast cancer." (PMID 35099410, 2022). "The seed genes in the functional modules, SRC and VDR were found to be upregulated in cancer tissue samples compared to normal breast samples." (PMID 35273218, 2022). "It is suggested that response to vitamin D supplementation in cancer modulated via vitamin D receptor." (PMID 35356739, 2022). "The tumor-suppressing and differentiation-inducing activities of VDR has been shown and generalized to many cancer cell lines." (PMID 36296975, 2022). "TLR/VDR polymorphisms and presence of microbial DNA in CRC patients highlight their role in cancer development and progression." (PMID 36139567, 2022). "The active forms of vitamin D3 (calcitriol and tacalcitol) coupled to the vitamin D receptor (VDR) are known to exhibit anti-cancer properties." (PMID 35053549, 2022). "Vitamin D receptor (VDR) is highly expressed in PDAC stroma, including among cancer-associated fibroblasts (CAFs), which are promoters of PDAC growth and aggressiveness." (PMID 35681565, 2022). "Vitamin D Receptor (VDR) is a nuclear receptor involved in the regulation of human metabolism, immunity, and cancer." (PMID 35807844, 2022). "VDR influences the proliferation of cancer cells at different stages, as well as their microenvironment, including immune cells and fibroblasts, and addresses several tumor-relevant pathways." (PMID 36364774, 2022). "In colorectal cancer (CRC), a study also indicates the similar relationship between ApoM and VDR but the role of ApoM in the cancer remains controversial." (PMID 36506554, 2022). "A VDR-mediated enhanced response to cisplatin treatment by VitD has been also suggested for other cancer types, potentially involving the NFκB pathway." (PMID 36291915, 2022). "More work is needed on assessing the integrity of tumour VDR signalling in cancer and trials are necessary to assess the safety of vitamin D3 supplementation, including small dose, in tumours with defective VDR signalling." (PMID 35445563, 2022). "Our results show that in both the genotypic and the recessive models, patients carrying the VDR BsmI rs1544410-AA genotype had a lower risk of developing NSCLC; the data were adjusted to take account of smoking status and family history of cancer." (PMID 36364930, 2022). "We are aware that VitD/VDR has been suggested to affect various cancer-relevant signaling pathways, such as Akt- and/or mTOR, which we did not analyze in detail here." (PMID 36291915, 2022).
cancer (continued). "Our study demonstrated a widely distributed VDR expression in bone metastases secondary to breast, prostate, renal, gastro-intestinal, follicular thyroid and further cancers." (PMID 36362766, 2022). "Calcipotriol has been shown to have anti-inflammatory and anti-cancer effects in pancreatitis and pancreatic cancer via VDR pathway." (PMID 35734414, 2022). "Taken together, further studies are required to validate and elucidate the role of VDR deficiency in the context of CVD and cancer risks, especially when modified by covariates associated with spaceflight, such as radiation." (PMID 35783863, 2022). "In comparison, breast (n = 16) and lung (n = 11) cancer bone metastases showed rather low nuclear and total VDR expressions." (PMID 36362766, 2022). "These direct vitamin D anti-cancer actions are mainly mediated through the binding of 1,25(OH)2D3 to the vitamin D receptor (VDR)." (PMID 36362766, 2022). "Various clinical and laboratory studies investigated the influence of VitD and its receptor VDR on cancer incidence, prognosis, aggressiveness, and therapy." (PMID 36291915, 2022). "There is a lot of data about VDR methylation in other cancers as well and most of it is at the observational level." (PMID 36246903, 2022). "The biologically active form of vitamin D interacts with the vitamin D receptor (VDR)coordinates the regulation of cancer cell proliferation, differentiation, and survival." (PMID 35399658, 2022). "We searched PubMed and Google Scholar using key words “vitamin D, VDR, tight junctions, cancer, inflammation, and infection”." (PMID 35406694, 2022). "On the other hand, cancer cells are believed to take up and activate 25-hydroxyvitamin D (25[OH]D) within the cell, which binds to the vitamin D receptor to regulate gene expression and consequently suppresses cancer growth." (PMID 35565657, 2022). "Immune cells such as lymphocytes, monocytes, macrophages, and dendritic cells express the VDR, which explains the major role of sufficient vitamin D levels for infections and cancer, respectively." (PMID 36726354, 2022). "Breast cancer, as the most common cancer in women worldwide, in particular is highly related to VDR regulation." (PMID 35111955, 2022). "The possible role of VDR in regulating immunity and the role of VDR in different cancer cells and diseases is reviewed in detail elsewhere." (PMID 35429253, 2022). "The following section sheds light on the anti-cancer effects of active VDR, resulting from epigenetic and transcriptomic changes and constituting a small part of all VDR effects in the human body." (PMID 36364774, 2022). "Studies in vitro and in vivo have shown inhibitory actions upon the binding of Calcitriol to the VDR for many different types of cancers." (PMID 35915393, 2022). "Active vitamin D (1,25(OH)2D3) is known to exert direct anti-cancer actions on various malignant tissues through binding to the vitamin D receptor (VDR)." (PMID 36362766, 2022). "This is likely to be valid for early developing cancers but, in more advanced cancer, we believe this concept should be tempered by VDR status." (PMID 35445563, 2022). "The epithelial-to-mesenchymal (EMT) transcription factors Snail1 and Snail2 (or Snail and Slug) have been shown to directly repress the VDR promoter in the context of cancer." (PMID 36146811, 2022). "Considering the heterogeneous effects of the cytokine, a more comprehensive analysis of TGFβ activity in tumoral cells is required, and the TGFβ–VDR feedback must be further demonstrated in cancer." (PMID 34208208, 2021). "The distribution of cytoplasmic and nuclear VDR is relevant to distinct biological activities, such as transcriptional regulation, immune regulatory process, anti-microbial activity and anti-cancer effects." (PMID 33553726, 2021). "Considering the molecular action and metabolism of vitamin D, VDR expression in cancer cells, it is very interesting how the vitamin affects cancer prognosis." (PMID 34208589, 2021).
cancer (continued). "Although previous studies reported correlations between cancer progression, Ca2+ activity and VDR signaling, the clear role of the VDR in the stomach, as well as its role in gastric homeostasis, remains obscure." (PMID 34439938, 2021). "VDR coexpression with AR and ER in cancer-surrounding breast tissue contributed to more favorable outcomes." (PMID 34638264, 2021). "Progressively reduced expression of VDR during dedifferentiation and tumor progression in many types of cancer has been observed." (PMID 34208589, 2021). "In prostate and other cancer types, several VDR-modulated genes can regulate the cancer development and progression." (PMID 34199743, 2021). "The results of the current study, to some extent, will highlight the discrepancies existing in the findings of different studies regarding vitamin D, VDR, and cancer by considering both the genetic and environmental aspects simultaneously." (PMID 34727991, 2021). "1α,25-dihydroxyvitamin D3 (VD3, also known as calcitriol), activated by binding to nuclear vitamin D receptor (VDR) in the genomic way, displays its wide-ranging effects on a variety of cancers." (PMID 34422809, 2021). "In line with our results, glycitein, a different benzopyranone, has been reported to upregulate the VDR in column cancer cells through Erk1/2." (PMID 33671804, 2021). "Other researchers have found that SNP rs4809957 located in the three untranslated regions of CYP24A1 gene 20q13.2 interacts with smoking, and 1,25(OH)2D3 plays an antiproliferation role on vitamin D receptor‐mediated human cancer cells." (PMID 34646549, 2021). "On the one hand, cancer cells present disturbances in expression of VDR and CYP27B1 that lead to disorders of vitamin D metabolism and action." (PMID 34208589, 2021). "The nuclear vitamin D receptor plays a role in the biology of cancer by affecting inflammatory microenvironment." (PMID 33906311, 2021). "It was proposed that increased CYP24A1 expression observed in cancer cells is probably mediated via activation of VDR, because both activity and expression of VDR are downregulated in most types of cancer." (PMID 34208589, 2021). "CYP27B1, the vitamin D metabolizing enzyme, was upregulated at the beginning of the cancer carcinogenesis process with an increased expression of the vitamin D receptor." (PMID 35127477, 2021). "Ingenuity pathway analysis identified autophagy and unfolded protein response (UPR) as top differentially expressed pathways between high and low VDR-expressing ER+ cancers." (PMID 34069442, 2021). "In cancer cells, VDR activation prevented epithelial mesenchymal transition and thereby maintained the epithelial cell character." (PMID 33671804, 2021). "In both normal and cancer prostate tissues, VDR is found to be lower both at level of transcription and translation compared to PDIA3." (PMID 33761087, 2021). "RAR and RXR are nuclear receptor transcription factors; RXRs heterodimerize with RARs and VDR and play important roles in regulation of genes that control cell proliferation, specifically in tumor or cancer cells." (PMID 33898466, 2021). "The expression of CYP27B1 in cancers also showed a similar trend giving a plausible explanation for the overexpression of VDR in cancer." (PMID 32679655, 2020). "Collectively, these data indicate that 1,25(OH)2D3, or VDR agonists in general, are candidates for cancer differentiation strategies." (PMID 32854355, 2020). "This work defines a novel role for 1,25D3 and the VDR in control of HA synthesis in epithelial tissues that likely contributes to its anti-cancer actions." (PMID 32774770, 2020). "The expression of VDR in cancer and in stromal cells is important for the inhibition of invasion of OC cells by vitamin D or its analogue, EB1089 (as found in VDR null mouse)." (PMID 33227893, 2020). "The anti-cancer effects of VDR has been shown to be exerted through different mechanisms among them are modulating expression of cancer-associated long non-coding RNAs (lncRNAs)." (PMID 32514489, 2020).